INS (insulin)
Diseases named in the same sentence as INS in open-access papers (continued):
Sharing a sentence is not in itself a finding about the gene and the disease.
type 2 diabetes (continued). "The aim of the current study was to examine the effect of limiting food intake to a feasible 10 h daily time frame for 3 weeks in free-living conditions on hepatic glycogen utilisation and insulin sensitivity in adults with type 2 diabetes." (PMID 35871650, 2022). "Skeletal muscle is the tissue responsible for the major portion of insulin-mediated glucose disposal, and insulin resistance is an essential defect contributing to the development of type 2 diabetes." (PMID 36381195, 2022). "Small pigs fed with high-fat diet and intravenously injected with STZ resulted in a stable animal model of type 2 diabetes, which is characterized by moderate hyperglycemia, hyperlipidemia, hypertension, and INS resistance." (PMID 35399795, 2022). "As NMDAR antagonists, like dextromethorphan, have been shown to increase serum insulin and lower blood glucose in type 2 diabetes patients, the potential signaling roles of these d-AAs through the NMDARs in human islets in vivo are suggested." (PMID 36144204, 2022). "A major paradox of type 2 diabetes is the selective impairment in the insulin mediated liver processes." (PMID 35058529, 2022). "Hypersecretion of the hormone insulin, either in the fasting or postprandial state, is believed to manifest several years before elevated blood glucose and type II diabetes mellitus." (PMID 36278750, 2022). "Here, we show that 8-weeks supervised HIIT combining rowing and cycling improved insulin sensitivity by ~30-40% not only in lean glucose-tolerant men, but also in obesity and type 2 diabetes with the same magnitude." (PMID 36387850, 2022). "Glucose uptake, a particularly important target in the treatment of type 2 diabetes, is mediated by insulin signaling and the AMPK pathway." (PMID 35565920, 2022). "In conclusion, this study presents for the first time a detailed analysis of the possible effect of the incretin hormones on insulin clearance in patients with type 2 diabetes." (PMID 35169165, 2022). "In healthy humans, beta-glucan consumption improved glycemic control and/or insulin response, and this has also being noticed in obese human patients and those with type II diabetes mellitus." (PMID 34980115, 2022). "MUFA-enriched diets reduce the requirement for insulin and decrease the plasma concentration of glucose and insulin in type 2 diabetic patients, compared with the effect of high SFA and low-fat, high cholesterol diets." (PMID 35454702, 2022). "A total of 111 patients with type 2 diabetes used oral hypoglycemic agents and 16 used insulin treatment (five of whom also used oral agents)." (PMID 35173604, 2022). "According to another study, 500 mg of berberine along with 5 gm of each glipizide and metformin in 60 type 2 diabetes patients is reported to enhance the state of glucose metabolism and insulin sensitivity by lowering the fasting blood glucose content." (PMID 36557843, 2022). "The studies also allowed to lower the level of fasting glucose, insulin, glucagon, triglycerides, and free fatty acids; in addition, there was an improvement in the level of glucose tolerance in mice with type 2 diabetes." (PMID 36012251, 2022). "Obesity can lead to chronic inflammation in different tissues, generating insulin and leptin resistance and alterations in glucose and lipid metabolism, favoring the development of degenerative diseases, including type II diabetes." (PMID 35112705, 2022). "In diabetic conditions, chronic hyperglycemia and consequent increase in ROS and cell death exacerbate type 2 diabetes by worsening cellular function and increasing insulin resistance." (PMID 35300109, 2022). "Type 2 diabetes mellitus (T2DM), a common metabolic disorder characterized by insulin resistance and inadequate insulin secretion by pancreatic β cells, has become a growing cause of morbidity and mortality worldwide." (PMID 35986429, 2022).
type 2 diabetes (continued). "SzkudelskaKet al, reported similar results, where they reported that resveratrol has improved insulin signaling in rats with congenital type 2 diabetes as well." (PMID 35781592, 2022). "GPR40 activation, which leads to insulin secretion, has become an attractive target for type 2 diabetes treatment." (PMID 36005597, 2022). "Two major diabetic types are type 1 diabetes (insulin defection from the problem of beta cells) and type 2 diabetes (insulin resistance from the inability of body cells)." (PMID 35163903, 2022). "S6K1 is a recognized signal molecule in the insulin signaling pathway PI3K/AKT/mTOR which plays an important role in the pathogenesis of type 2 diabetes." (PMID 36062190, 2022). "Decreased spliced XBP1 expression was observed in islets of type 2 diabetic patients and studies adopting embryonic deletion of Xbp1 using the rat insulin promoter showed that it is required for optimal beta cell development and proinsulin processing." (PMID 35316840, 2022). "The administration of 10–30 mg/day of pioglitazone for 6 months to AD patients accompanied with type 2 diabetes mellitus decreased fasting plasma insulin levels." (PMID 36547082, 2022). "This cross‐talk is defective in type 2 diabetes (T2D) due to a combination of failing β‐cell function, reduced insulin sensitivity and elevated endogenous glucose production." (PMID 36054466, 2022). "This study aimed to evaluate the effects of Insulin Degludec/Insulin Aspart (IDegAsp) as an intensification treatment for glycemic control in patients with type 2 diabetes (T2D) in a real-world clinical setting." (PMID 36992737, 2022). "Despite the established role of insulin in glycemia regulation and the pathophysiology of type 2 diabetes, tissue-specific Insr knockout models often depict certain important aspects of diabetic syndrome." (PMID 34801552, 2022). "The concept of metabolically ‘benign’ obesity with preservation of insulin sensitivity is established, with some studies identifying a favorable cardiometabolic profile with reduced incidence of type 2 diabetes compared to unhealthy obesity." (PMID 35957819, 2022). "Type 2 diabetes is a progressive disease characterized by a continuous decline in beta-cell function and insulin sensitivity starting years before diagnosis." (PMID 36104712, 2022). "The insulin secretion in type II diabetes is normal, but cells and tissues are resistant to insulin, which results in a spike in blood glucose levels." (PMID 36176638, 2022). "These six commonly identified KEGG pathways are type II diabetes mellitus, Insulin signaling, JAK-STAT signaling, Calcium signaling, Adipocytokine signaling, and Wnt signaling pathways." (PMID 37529091, 2022). "Whether amino acids act on cellular insulin signaling remains unclear, given that increased circulating amino acid levels are associated with the onset of type 2 diabetes (T2D)." (PMID 35879296, 2022). "But the use of insulin treatment was more common in patients with type 2 diabetes who had diabetic foot ulcers (p = 0.004)." (PMID 36945977, 2022). "Several studies have demonstrated associations between serum PFAS concentrations and glycemic indicators of type 2 diabetes including glucose, insulin, and HOMA-IR in adolescent and adult cohorts." (PMID 35992116, 2022). "Type-2 diabetes is characterized by insensitivity to insulin, declining insulin production and eventual pancreatic beta-cell failure, leading to reductions in glucose transport into the liver." (PMID 35457335, 2022). "Type 2 diabetes is a chronic disease with elevated blood sugar mainly due to impaired biological action and/or insufficient secretion of insulin." (PMID 35571731, 2022). "Adiponectin concentrations have been negatively correlated with fasting insulin concentrations and positively correlated with insulin sensitivity, and are considered closely related to the pathophysiology of type 2 diabetes in humans." (PMID 35968003, 2022).
type 2 diabetes (continued). "Insulin resistance in obesity and type 2 diabetes mellitus (T2DM) is characterized by decreased insulin-stimulated glucose transport and metabolism in adipocytes and skeletal muscle." (PMID 36467416, 2022). "Fructose causes the smallest increase in postprandial plasma glucose, postprandial glucose area, and serum insulin level when compared to other types of carbohydrate in healthy subjects and type 2 diabetic patients." (PMID 35227323, 2022). "The GLP-1-related beta-cell mass retention is a crucial process in saving insulin response in type 2 diabetes." (PMID 36670938, 2022). "In the 1950’s, Dr. I. Arthur Mirsky first recognized the possible importance of insulin degradation changes to the pathogenesis of type 2 diabetes." (PMID 35163746, 2022). "Again, we found limited evidence to support mediation by liability to type 2 diabetes for all traits apart from fasting insulin (proportion mediated: 70%)." (PMID 35129650, 2022). "This article describes the results of a 18‐week double‐blind clinical trial, assessing the effects of imeglimin on insulin secretion and sensitivity using an oral glucose tolerance test in Caucasian Type 2 Diabetic patients." (PMID 36239048, 2022). "In one middle-east study, fasting-lipid-profile, hemoglobin A1c, serum leptin, insulin, and glucose levels were measured among type 2 diabetic patients." (PMID 36295022, 2022). "This includes the vast population of patients with type 2 diabetes who use glucometers for point-in-time measurements of the blood glucose and insulin pens for multiple daily injections." (PMID 35941355, 2022). "The insulinogenic index and its composite with insulin sensitivity (disposition index) have been demonstrated to be predictive of type 2 diabetes." (PMID 36557270, 2022). "When insulin levels are increased, such as in type 2 diabetes, insulin uses the majority of IDE, and undegraded amyloid-β starts to accumulate in neurons." (PMID 36232867, 2022). "Type 2 diabetes (T2D) is a complex metabolic disease characterized by hyperglycemia due to defects in insulin secretion, action, or both." (PMID 36553674, 2022). "The prevalence of hypomagnesemia in type 1 diabetes in the present cohort is significantly lower than in type 2 diabetes adults (13.5–47.7%) and historic cohorts of insulin-treated outpatients with diabetes." (PMID 35440685, 2022). "Type 2 diabetes is a disease that requires a high level of both patient and provider monitoring of nutrition, exercise, weight control, blood glucose, and insulin levels." (PMID 36316151, 2022). "GlucoTab@MobileCare, a digital workflow and decision support system with integrated basal and basal-plus insulin algorithm was investigated for user acceptance, safety and efficacy in persons with type 2 diabetes receiving home health care by nurses." (PMID 36992745, 2022). "In type 2 diabetes (T2D), both insufficient insulin secretion in the pancreas and an impaired insulin sensitivity of the liver and skeletal muscle contribute to the observed hyperglycemia." (PMID 36557261, 2022). "Many population-based clinical studies have shown that intensive insulin therapy in patients with type 2 diabetes can help normalize blood glucose control in the short term, thus delaying the progression of DR." (PMID 35459162, 2022). "Studies conducted in multiple cell types confirmed that insulin-sensitizing TZDs that had been developed for treatment of type 2 diabetes acted as inhibitors of MPC activity by directly binding to the MPC complex." (PMID 35782864, 2022). "The body of a diabetic person either cannot effectively use the produced insulin (type I diabetes) or cannot produce enough insulin (type II diabetes)." (PMID 35458005, 2022). "The purpose of this study was to find the endogenous insulin secretory capacity and a possible predictor of insulin withdrawal in subjects with type 2 diabetes requiring hospitalization due to hyperglycemia." (PMID 35574023, 2022).
type 2 diabetes (continued). "Type 2 diabetes mellitus (T2DM) is a type of metabolic disorder that includes chronic hyperglycemia resulting from insulin insensitivity on appropriate tissues." (PMID 35056687, 2022). "Insulin signaling controls cell growth and metabolism, and dysregulation of this pathway is a common feature of type 2 diabetes (T2D), obesity, and metabolic syndrome." (PMID 36473871, 2022). "Ciliopathies, human diseases characterized by cilia dysfunction, manifest, type 2 diabetes, among other features, suggesting a role of the cilium in insulin signaling." (PMID 35902579, 2022). "significantly increased the phosphorylation levels of key proteins in the insulin signaling pathway in type 2 diabetes and had a significant inhibitory effect on SHP-1." (PMID 35957821, 2022). "We recommend the use of basal insulin analogues, instead of NPH, for all patients with type 2 diabetes needing treatment with basal insulin." (PMID 35288805, 2022). "In conclusion, subjects with type 2 diabetes presented expected changes in insulin, glucagon and GLP-1 levels after breakfast and a single aerobic exercise session, not accompanied by glycemic variability changes." (PMID 35612843, 2022). "Insulin clearance is reduced in obesity and type 2 diabetes, which leads to a state of hyperinsulinemia." (PMID 35328759, 2022). "In abdominally obese individuals, enriched seafood sticks induce a potential protection against type 2 diabetes development by the reduction in the insulin and HOMA-IR; and in cardiovascular disease, in women, by the PP reduction." (PMID 35643872, 2022). "During hospitalization, 77.9% of patients with type 2 diabetes had followed lifestyle and dietary measures with insulin therapy and 22.1% lifestyle and dietary measures alone." (PMID 36250928, 2022). "MetS goes from disturbances in the glucose metabolism to comorbidities such as obesity, arterial pathology and dyslipidemia; it finally triggers type 2 diabetes and cardiovascular diseases, illustrated by higher insulin and C-peptide levels." (PMID 35334615, 2022). "Previous aerobic-prescribed trials in PCOS, type 2 diabetes, and/or obesity have shown significant reductions in fasting insulin and fasting glucose." (PMID 35547420, 2022). "Pancreatic β-cell-specific PDX1 deficiency in mice leads to the reduced expression of insulin and SLC2A2, causing maturity-onset diabetes." (PMID 36361703, 2022). "Dipeptidyl peptidase 4 (DPP4) inhibitors can treat type 2 diabetes by slowing GLP-1 degradation to increase insulin secretion." (PMID 35629891, 2022). "Type 2 Diabetes Mellitus (T2DM) is defined as relative insulin deficiency secondary to pancreatic β-cell dysfunction and also insulin resistance in specific organs." (PMID 36316667, 2022). "Insulin therapy was started in the post-transplant period in 2 of the other type 2 diabetes patients who used oral antihyperglycemic drugs and in one patient who only took a diet before transplantation." (PMID 36402951, 2022). "The pubertal pediatric population has the physiologically lowest insulin sensitivity and the highest incidence of type 2 diabetes." (PMID 36589801, 2022). "In patients with type 2 diabetes, an overnight infusion of somatostatin gave the beta cell a rest from constant stimulation by insulin and restored insulin pulse mass and normal insulin secretion." (PMID 35163806, 2022). "Insulin is often used in people with type 2 diabetes when glycemic control is still insufficient despite up-titration to maximal doses of dual therapies, which are usually metformin plus sulfonylureas or DPP-4i." (PMID 35933524, 2022). "Thiazolidinediones (TZDs) are PPARγ synthetic ligands with insulin-sensitizing properties, used for the treatment of type 2 diabetes." (PMID 36358540, 2022). "In a cohort of obese South Korean patients, CEACAM1, a major player in promoting insulin clearance, was reported to be progressively reduced with increased hepatic steatosis independently of type 2 diabetes." (PMID 36009446, 2022).
type 2 diabetes (continued). "Another study showed that oral metformin altered the gut microbiome composition in obese adults with type 2 diabetes (T2D) which was associated with secondary BA and FXR changes, resulting in improved insulin sensitivity." (PMID 35873174, 2022). "We report the impact of COVID-19 lockdown (between 22/3/2020 and 24/6/2020) on glucose control pre- and postlockdown and during Ramadan, in patients with type 1 diabetes (T1D) and type 2 diabetes (T2D) on insulin therapy." (PMID 35433783, 2022). "We also examined the characteristics of outpatients with type 2 diabetes requiring insulin therapy after 4 years, which, to the best of our knowledge, is the longest observational period in such studies." (PMID 35229479, 2022). "Insulin therapy is essential to the treatment of type I diabetes (T1D) and some type II diabetes (T2D)." (PMID 35372263, 2022). "Glucose-stimulated insulin secretion (GSIS) is a tightly regulated process, and GSIS impairment is a hallmark of type 2 diabetes (T2D)." (PMID 35327599, 2022). "Exercise training improves whole-body energy homeostasis by enhancing skeletal muscle metabolic flexibility and insulin sensitivity and is therefore an efficacious intervention to improve glucose regulation in individuals with type 2 diabetes." (PMID 36070371, 2022). "In type 2 diabetes, there is evidence for the existence of β-cells that have reduced insulin expression and/or lack the expression of other markers of β-cell function, which has been taken to supporting the existence of dedifferentiated β-cells." (PMID 35327373, 2022). "The incidence of insulin‐based metabolic diseases, such as type II diabetes and hyperinsulinemia, has increased rapidly in the past decades." (PMID 36111501, 2022). "The glucose uptake by fibroblasts in obese patients with type II diabetes has been increased by 50% compared to the healthy control, while insulin-dependent glucose uptake was reduced by as much as 3-fold." (PMID 35328751, 2022). "Thiazolidinediones (TZD) improve insulin sensitization and glucose homeostasis mediated by the activation of peroxisome proliferator-activated receptors γ (PPARγ) in patients with type 2 diabetes." (PMID 37746194, 2022). "Some of the etiopathogenetic mechanisms involved in the development of SDB in type 2 diabetes, such as insulin resistance and low-grade inflammation, are also part of the prediabetes environment." (PMID 35268504, 2022). "Exogenous insulin is considered in patients with type 1 diabetes, while many classes of glucose-lowering agents are used for patients with type 2 diabetes." (PMID 35163903, 2022). "One would expect that since insulin is the cornerstone of type 1 diabetes care, type 1 diabetics will be more hesitant to give up its intake in comparison to type 2 diabetics, especially those on OAD, for whom insulin is less important." (PMID 35573427, 2022). "Type 2 diabetes induction in C57BL/6J mice by a high-fat diet resulted in increased plasma insulin, increased blood glucose levels, as well as reduced GLUT4 mRNA expression indicating impaired plasma glucose clearance." (PMID 35055468, 2022). "A critical decline of functional insulin-producing pancreatic β-cells is the central pathologic element of both type 1 and type 2 diabetes." (PMID 35370966, 2022). "Adiponectin is considered to be one of the cytokines that contributes to the development of insulin sensitivity, and lower levels of adiponectin have been found in patients with obesity and type 2 diabetes." (PMID 35312173, 2022). "Model 1 includes the effects of the group (treatment/control) and income quintile on insulin initiation in individuals with type 2 diabetes." (PMID 36033350, 2022). "ß-cell damage by fatty acids and the subsequent reduction in insulin secretion appears to be an early event in the pathogenesis of hyperglycemia in type 2 diabetes." (PMID 35159354, 2022).